KDM2A (lysine demethylase 2A)
Diseases named in the same sentence as KDM2A in open-access papers (continued):
Sharing a sentence is not in itself a finding about the gene and the disease.
diabetes (5 papers, 2012 to 2025). "We identify an interaction between a TCF7L2 intronic SNP and PGS SNPs altering sites bound by the KDM2A TF for glycated haemoglobin (HbA1c) levels, a biomarker of blood glucose widely used in the diagnosis and management of diabetes." (PMID 41332835, 2025). "Furthermore, diabetes databases indicate low KDM2A expression in pancreatic islets, adipose tissue, liver, skeletal muscle, and the hypothalamus." (PMID 37892137, 2023). "Thus, in this study, we established a novel liver-specific Kdm2a KO mouse model to evaluate whether deficiency of KDM2A in the liver leads to increased expression of NF-κB target genes and abnormal liver function, which are characteristic of metabolic disorders and diabetes." (PMID 37892137, 2023).
Insulin resistance (5 papers, 2012 to 2025). Increased resistance towards insulin, that is, diminished effectiveness of insulin in reducing blood glucose levels. "Furthermore, inhibition of miR-721 in high-fat diet-induced insulin-resistant mice resulted in restoration of KDM2A levels, concomitantly reducing FOXO1, PCK1, and G6PC expression, attenuating gluconeogenesis, hyperglycemia, and improving glucose tolerance." (PMID 38745315, 2024). "Interestingly, the epigenetic modulator laccaic acid also reduced the hepatic miR-721 expression and improved KDM2A expression, supporting our earlier report that laccaic acid attenuates insulin resistance by reducing gluconeogenesis." (PMID 38745315, 2024). "Interestingly, our ChIP experiments revealed that palmitate-induced insulin resistance increased the enrichment of H3K36me2 around FOXO1 promoter along with reduced expression of Kdm2a, which was restored by miR-721 inhibition." (PMID 38745315, 2024). "Our study unveils the role of miR-721 in regulating gluconeogenesis through KDM2A and FOXO1 under insulin resistance, pointing towards significant clinical and therapeutic implications for metabolic disorders." (PMID 38745315, 2024). "Additionally, we report that laccaic acid could attenuate insulin resistance and reduce gluconeogenesis via altering H3K36me2 methylation around the FOXO1 promoter by reducing the elevated miR721 and restoring KDM2A/FOXO1 axis." (PMID 38745315, 2024).
breast tumor (4 papers, 2014 to 2021). "Knockdown of KDM2A completely abolished the tumour-promoting activity of CAFs on breast tumour growth in vivo and diminished PD-L1 expression in the stroma of tumour tissues." (PMID 33024266, 2021). "We performed immunohistochemical staining to investigate the expression of KDM2A in 202 breast tumor tissues." (PMID 27029061, 2016). "Interestingly, when we checked KDM2A expression in human breast tumour tissues, we found that KDM2A is also highly upregulated in CAFs." (PMID 33024266, 2021). "Immunohistochemical staining showed that KDM2A was highly expressed in some breast tumour tissues." (PMID 33024266, 2021). "Ductal cells of the breast tumors also show KDM2A expression but at considerably lower levels." (PMID 25029110, 2014). "Whether the same mechanism holds true for the metastatic breast tumors overexpressing KDM2A needs to be evaluated." (PMID 25029110, 2014).
cervical carcinoma (4 papers, 2010 to 2024). A carcinoma arising from either the exocervical squamous epithelium or the endocervical glandular epithelium. "An up-regulated expression of KDM2A was also shown to play a critical role in the onset and progression of cervical cancer and promote the proliferation and invasion of cervical cancer cells." (PMID 34391411, 2021). "KDM2A upregulation is induced by HPV16 E7 and promotes the proliferation and invasion of cervical cancer cells, indicating a poor prognosis." (PMID 39684425, 2024).
colorectal cancer (4 papers, 2019 to 2023). A primary or metastatic malignant neoplasm that affects the colon or rectum. "SP1 upregulated lncRNA TUG1 and promoted the tumorigenesis of colorectal cancer cells by TUG1/miR-421/lysine demethylase 2A (KDM2A)/ERK axis." (PMID 37686205, 2023).
glioma (4 papers, 2022 to 2024). A benign or malignant brain and spinal cord tumor that arises from glial cells (astrocytes, oligodendrocytes, ependymal cells). "Long noncoding RNA homeobox A cluster antisense RNA 2 (lncRNA HOXA-AS2), which has been found to be elevated in glioma tissues, upregulated KDM2A by inhibiting miR-302a’s ability to bind to the 3′ untranslated region of KDM2A." (PMID 39765675, 2024). "RT-qPCR and IHC results presented that JAG1 mRNA and protein expression was high in glioma tissues and shared a positive correlation with KDM2A expression in glioma tissues." (PMID 35181676, 2022). "lncRNA HOXA-AS2 promotes Treg proliferation and immune tolerance through the miR-302A/KDM2A axis to promote glioma progression and poor prognosis." (PMID 36468039, 2022). "In our study, we found that KDM2A expression was elevated in glioma biopsy specimens and glioma cell lines and that lncRNA HOXA-AS2 positively regulated the expression of KDM2A to promote glioma cell proliferation and immune tolerance." (PMID 35181676, 2022). "Taken together, our study demonstrated that lncRNA HOXA-AS2 promoted glioma progression in vivo by mediating the miR-302a/KDM2A/JAG1 axis." (PMID 35181676, 2022). "To investigate the role of the lncRNA HOXA-AS2/miR-302a/KDM2A/JAG1 axis in glioma progression, we established a xenograft mouse model, in conjunction with lncRNA HOXA-AS2 silencing and JAG1 overexpression." (PMID 35181676, 2022). "Collectively, lncRNA HOXA-AS2 can promote glioma cell proliferation and immune tolerance to accelerate glioma progression by orchestrating the miR-302a/KDM2A axis." (PMID 35181676, 2022). "Abundant data have revealed that KDM2A acts as an oncogene to promote the progression of various cancers, including glioma." (PMID 35181676, 2022). "The upregulation of KDM2A contributed to regulatory T-cell proliferation and immune tolerance in glioma samples and a tumor xenograft mouse model as it demethylated the jagged 1 (JAG1) promoter region, elevating JAG1 expression and contributing to regulatory T-cell proliferation." (PMID 39765675, 2024). "Downregulation of KDM2A is also a promising target for glioma and GBM treatment." (PMID 39765675, 2024). "Furthermore, RT-qPCR data depicted higher KDM2A expression in glioma tissues than in normal brain tissues." (PMID 35181676, 2022). "To further identify the function of lncRNA HOXA-AS2/miR-302a/KDM2A axis in glioma progression, we silenced lncRNA HOXA-AS2 using sh-lncRNA HOXA-AS2 and restored KDM2A expression using oe-KDM2A or repressed miR-302a using miR-302a inhibitor in LN229 and A172 cells." (PMID 35181676, 2022). "KDM2A silencing has been shown to inhibit the proliferation, migration and invasion of glioma cells, suggesting the oncogenic role of KDM2A in the progression of glioma." (PMID 35181676, 2022). "We found aberrant upregulation of lncRNA HOXA-AS2, lysine demethylase 2A (KDM2A), and jagged 1 (JAG1) and a downregulation of microRNA-302a (miR-302a) in glioma specimens." (PMID 35181676, 2022). "In summary, our investigation revealed that lncRNA HOXA-AS2 upregulated KDM2A expression and promoted JAG1 expression in glioma cells by competitively binding to miR-302a." (PMID 35181676, 2022). "To conclude, lncRNA HOXA-AS2 facilitates KDM2A/JAG1 expression to promote Treg cell proliferation and immune tolerance in glioma by binding to miR-302a." (PMID 35181676, 2022). "The lncRNA HOXA-AS2 can enhance the expression of KDM2A/JAG1, which can contribute to Treg cell proliferation and immune tolerance in gliomas and promote tumor development." (PMID 36468039, 2022). "Regarding potential therapies for glioma and GBM, upregulating miRNAs could reduce stemness and progression, as the overexpression of miR-663a inhibited the KDM2A/TGF-β/Smad signaling pathway." (PMID 39765675, 2024). "Additionally, multiple KDM2A and KDM2B studies have demonstrated that miR-663a, miR-302a, and miR-let-7b downregulation resulted in the tumorigenesis of GBM and glioma." (PMID 39765675, 2024).
glioma (continued). "Additionally, more research could be conducted to confirm the downstream genetic targets of the KDM2A/TGF-β/Smad pathway and the KDM2A/JAG1 axis in GBM and glioma to improve treatments and mitigate their secondary effects in patients." (PMID 39765675, 2024).
hepatocellular carcinoma (4 papers, 2012 to 2026). A malignant tumor that arises from hepatocytes. "Likely in hepatocellular carcinoma, specific lncRNAs recruit polycomb proteins (EZH2, SUZ12) and histone demethylases (KDM2A) to FGFR2 loci, facilitating exon IIIb inclusion and favoring tumor-suppressive isoform expression." (PMID 41584352, 2026). "A recent study revealed that by inhibiting lysine demethylase 2A (KDM2A)-mediated demethylation of H3K26m2, ZHX2 downregulates the expression of stemness genes, including EPCAM, in hepatocellular carcinoma stem cells." (PMID 38791091, 2024).
bladder cancer (3 papers, 2022 to 2024). "The results indicate that the change of gene expression caused by KD of KDM2A can be partially restored by KD RARRES3.These findings suggested that KDM2A facilitates bladder cancer cell proliferation and invasion by inhibiting RARRES3 expression." (PMID 35697678, 2022). "A total of 5% of bladder cancer patients have KDM2A mutations which are frequently amplified." (PMID 35697678, 2022). "In bladder cancer, knockdown of KDM2A which is capable of restraining RARRES3, diminishes high-grade bladder cancer cell growth, aggressiveness, and spheroid formation." (PMID 38462627, 2024). "KDM2A silencing significantly increased H3K36me2 modification at the RARRES3 locus in high-grade bladder cancer cells." (PMID 35697678, 2022). "Taken together, these results suggested that KDM2A KD significantly reduced high-grade bladder cancer cell proliferation and metastasis." (PMID 35697678, 2022). "To investigate the effects of KDM2A depletion in high-grade bladder cancer cells, we stably silenced KDM2A in high-grade bladder cancer cell lines (UMUC3 and 5637) using two specific shRNAs." (PMID 35697678, 2022). "KDM2A knockdown (KD) decreased the proliferation, invasion, and spheroid formation of high-grade bladder cancer cells and inhibited tumor growth in mouse xenograft models." (PMID 35697678, 2022). "To investigate the role of RARRES3 in the phenotypes of bladder cancer cells regulated by KDM2A, we subcutaneously injected the shCtrl and shRARRES3 UMUC3 cells into nude mice." (PMID 35697678, 2022). "In summary, we provide novel evidence for the role of SE-driven KDM2A in modulating high-grade bladder cancer malignant phenotypes." (PMID 35697678, 2022). "Next, we found that the expression of KDM2A in primary and recurrent bladder cancer was significantly higher than that in paracancerous tissues." (PMID 35697678, 2022). "H3K27ac ChIP-seq analysis revealed a specific super-enhancer (SE) at the KDM2A locus in high-grade bladder cancer." (PMID 35697678, 2022). "Here, we revealed a positive correlation between KDM2A gene copy number gain and upregulation of KDM2A mRNA expression in bladder cancer." (PMID 35697678, 2022). "Intriguingly, high-grade bladder cancer showed higher KDM2A expression than low-grade bladder cancer." (PMID 35697678, 2022). "Intriguingly, RARRES3 KD attenuated the inhibitory effects of KDM2A depletion on the malignant phenotypes of high-grade bladder cancer cells." (PMID 35697678, 2022). "Our analysis showed that KDM2A copy number gain most likely contributes to the formation of SE at KDM2A, which leads to a high expression level of KDM2A in high-grade bladder cancer." (PMID 35697678, 2022). "Here, we report a positive correlation between the increase in KDM2A expression and gain in gene copy number in bladder cancer." (PMID 35697678, 2022). "The study also identified the KDM2A/RARRES3 axis as a potential therapeutic target for the treatment of high-grade bladder cancer." (PMID 35697678, 2022). "The protein level of KDM2A in high-grade bladder cancer was higher than that in low-grade bladder cancer." (PMID 35697678, 2022). "Another study indicated that IOX1 could also inhibit KDM2A to reduce the proliferation and invasion of bladder cancer cells in vitro and in vivo." (PMID 38086789, 2023). "Targeting the KDM2A/RARRES3 axis may be a promising therapeutic strategy for high-grade bladder cancer." (PMID 35697678, 2022). "Importantly, RARRES3 expression negatively correlated with the mRNA expression of KDM2A in bladder cancer." (PMID 35697678, 2022). "Moreover, a super-enhancer (SE) driving KDM2A transcription was found in high-grade bladder cancer, resulting in a significantly higher expression of KDM2A mRNA compared to that in low-grade bladder tumors." (PMID 35697678, 2022). "Moreover, we confirmed the formation of SE at the KDM2A locus in high-grade bladder cancer in surgical specimens from patients with bladder cancer." (PMID 35697678, 2022).
bladder cancer (continued). "Our findings revealed that targeted restoration of H3K36me2 of RARRES3 via KDM2A inhibition could restrain malignant progression in high-grade bladder cancer." (PMID 35697678, 2022). "Subsequently, KDM2A KD impaired bladder cancer cell proliferation, sphere formation, and migration." (PMID 35697678, 2022). "Interestingly, our data indicates that KDM2A inhibition combined with RARRES3 activation can be a useful therapeutic strategy for high-grade bladder cancer." (PMID 35697678, 2022). "Our findings support the notion that KDM2A blockade combined with ATRA treatment may be a promising therapeutic strategy for high-grade bladder cancer." (PMID 35697678, 2022). "In addition, there was a positive correlation between KDM2A mRNA expression and KDM2A gene copy number gain in patients with bladder cancer." (PMID 35697678, 2022). "Additionally, we analyzed TCGA bladder cancer datasets and found that the proportion of KDM2A amplification and gain alteration in high-grade bladder cancer was significantly higher than that in low-grade bladder cancer." (PMID 35697678, 2022). "Moreover, we included the data of KDM2A knockdown (KD) on proliferation, invasion, spheroid formation, tumorigenesis, and mRNA expression to characterize the functions of KDM2A in high-grade bladder cancer." (PMID 35697678, 2022). "Thus, we conducted the current research with the hypothesis that KDM2A-mediated H3K36me2 demethylation of RARRES3 stimulates the progression of bladder cancer with its role in cell growth and metastasis." (PMID 35697678, 2022). "Importantly, the KDM2A locus is found driven the SE in both high-grade bladder cancer cell lines." (PMID 35697678, 2022). "Surprisingly, KDM2A inhibition, together with ATRA, synergistically reduced the viability of high-grade bladder cancer cells." (PMID 35697678, 2022). "In bladder cancer, RARRES3 expression was negatively correlated with KDM2A and was significantly downregulated." (PMID 35697678, 2022). "However, the function of KDM2A in bladder cancer remains largely unknown." (PMID 35697678, 2022). "However, the efficacy of the KDM2A inhibitors IOX1 and ATRA in the treatment of high-grade bladder cancer cells is limited." (PMID 35697678, 2022). "This study identified several key targets of KDM2A, including RARRES3, which has not been previously reported in high-grade bladder cancer." (PMID 35697678, 2022).
clear cell renal cell carcinoma (3 papers, 2021 to 2022). "Our study aimed to explore the expression and the biological role of lysine-specific demethylase 2A (KDM2A) in clear cell renal cell carcinoma (ccRCC)." (PMID 34391411, 2021).
male infertility (3 papers, 2024 to 2025). The inability of the male to effect fertilization of an ovum after a specified period of unprotected intercourse. "Using conditional deletion approaches, we demonstrate that Kdm2a deficiency leads to testicular atrophy and male infertility." (PMID 40701999, 2025). "In the current study, we revealed that loss of the demethylase KDM2A results in defective male meiosis and male infertility." (PMID 39160277, 2024). "Conditional knockout of KDM2A leads to complete male infertility, as spermatogenesis ultimately halts during the fertilization stage of meiosis." (PMID 39595990, 2024).
type 2 diabetes (3 papers, 2012 to 2023). "They found that metformin (a drug used to treat type 2 diabetes) activated KDM2A by increasing AMPK activity, which led to a decrease in cell proliferation." (PMID 37726685, 2023). "Kdm2a has been reported to negatively regulate the expression of gluconeogenic genes in hepatocytes and mice and, thus, speculated to protect against diseases like Type 2 diabetes." (PMID 37892137, 2023).
asthma (2 papers, 2025). "Indeed, roles for other epigenetic effectors, including histone methylation and acetylation marks, have been implicated in the severity of asthma, and a genome-wide association study identified significant histone modifying enzyme (KDM2A, KDM4C, HDAC4, HDAC7 and HDAC9) polymorphisms in asthma." (PMID 40057553, 2025).